GOT2 (glutamic-oxaloacetic transaminase 2)
Diseases named in the same sentence as GOT2 in open-access papers (continued):
Sharing a sentence is not in itself a finding about the gene and the disease.
tumor (continued). "In the present study, we demonstrated for the first time that BRCA1 formed a co‐repressor complex with ZBRK1 on the promoter of GOT2 via the ZBRK1 recognition element, and that BRCA1 deficiency promoted aspartate and α‐KG production and accelerated tumor cell growth along with GOT2 upregulation." (PMID 30714292, 2019). "One may propose that GOT2 is fine‐tuned with different cell metabolic status and different stimuli in the tumor microenvironment." (PMID 30714292, 2019). "The GOT2 tumour was confirmed in the IHC analyses by markers for MTC." (PMID 31725814, 2019). "GOT2, a classical mitochondrial metabolic enzyme, has recently become a major research focus in the field of moonlighting enzymes due to its significant temporal and spatial dynamic regulation characteristics in tumor microenvironments and metabolic remodeling processes." (PMID 40842990, 2025). "Hence, we hypothesized that GOT2 might have a modest effect on tumor biological behavior in cancer cells." (PMID 37693904, 2023). "Therefore, we speculated that the circRNA hsa_circ_0002130 might act as a miRNA sponge to increase the expression of GOT2, thereby inhibiting the tumor cell growth via gluconeogenesis." (PMID 34094907, 2021). "In contrast, GOT2, EHHADH, and APOA1 were associated with better survival outcomes and were significantly downregulated in HCC tissues, as well as positively correlated with tumor stage, grade, age, and sex, suggesting that these three MRGs were tumor suppressor genes." (PMID 34869039, 2021). "Furthermore, we also found that hsa_circ_0002130 could efficiently inhibit tumor cell growth and promote GOT2 expression, further suggesting that hsa_circ_0002130 might act as a tumor suppressor in HCC." (PMID 34094907, 2021). "By simultaneously regulating tumor metabolic reprogramming (maintaining aspartate supply) and redox homeostasis (regulating NAD+ regeneration), GOT2 has emerged as a promising anticancer target." (PMID 40842990, 2025). "We also confirmed that STUB1 or GOT2 were indeed overexpressed or knocked down and STUB1 overexpression increased GOT2 expression in respective tumor tissues." (PMID 40651940, 2025). "Therein, the mitochondrial enzyme glutamic-oxaloacetic transaminase-2 (GOT2) bound to fatty acid ligands and stimulated PPARδ’s transcriptional activity, leading to the spatial exclusion of CD4+CD8+ T cells from the tumor tissue." (PMID 37833991, 2023). "Depletion of glutamic-oxaloacetic transaminase 2 (GOT2) breaks the redox balance and inhibits PDAC cell growth in vitro, but it has little effect on tumor growth in vivo." (PMID 36230914, 2022). "Acetylation of GOT2 stimulates NADPH production and promotes pancreatic cell proliferation and tumor growth in vivo." (PMID 36712965, 2022). "Next, to focus our analysis on KIRC, we investigated the transcription levels of GOT2 performing a single-gene differential analysis using RNA-seq data from the TCGA database (KIRC-TCGA), compared with non-tumor tissues from the GTEx database by GEPIA2." (PMID 35735610, 2022). "Compared with peri-tumor samples, GAD1, SPP1, and WFS1 were significantly upregulated in tumor tissues, and GOT2, EHHADH, and APOA1 were significantly downregulated in tumor tissues." (PMID 34869039, 2021). "GAD1, SPP1, and WFS1 were upregulated, whereas GOT2, EHHADH, and APOA1 were downregulated in HCC samples compared with peri-tumor controls, and this was consistent with the results in the ICGC, GSE14520, GSE54236, GSE107170, and GSE36376, validation datasets." (PMID 34869039, 2021). "In contrast, GOT2, EHHADH, and APOA1 were significantly negatively correlated with tumor infiltrating immune cells." (PMID 34869039, 2021). "For 7 SCC-distinguishing enzymes (ASNS, GAPDH, GOT2, IDH2, ME1, PSAT, and TPI) protein levels were increased in MYC+N1ICD tumours compared with the normal lungs." (PMID 31114017, 2019).
tumor (continued). "Based on accumulating evidence, ASNS, GOT2, and GLS, as well as asparagine, substantially contribute to tumor growth and metastasis." (PMID 30858360, 2019). "In this study, we provide evidence that STUB1 acts as a suppressor of tumor cell proliferation by controlling aspartate biosynthetic pathways through GOT2, not GOT1." (PMID 40651940, 2025). "In PDAC, while GOT2 knockdown significantly suppresses tumor cell proliferation in vitro, it does not impair tumor growth in xenograft or orthotopic mouse models." (PMID 40842990, 2025). "Downregulation of GLS, GOT2, and ASNS effectively blocks SOX12-mediated CRC cell proliferation and metastasis, while ectopic expression of these enzymes reverses the inhibitory effects of SOX12 knockdown on tumor progression." (PMID 40842990, 2025). "Moreover, several pivotal enzymes involved in amino acid metabolism process and urea cycle were identified with decreased lysine acetylation levels in HCC tumor tissues, such as GLUD1, ASL, GOT2 and so on." (PMID 33093847, 2020). "In vivo tumorigenesis experiments revealed significant decreases in tumor growth, tumor weight, and Ki67-positive staining upon silencing of GLS, GOT2, or ASNS in SW480-SOX12 cells, whereas GLS, GOT2, or ASNS overexpression reversed the SOX12 knockdown-induced suppression of tumor growth." (PMID 30858360, 2019). "Although current research on GOT2-related sulfur metabolism has primarily focused on non-cancerous diseases, whether a similar mechanism operates in tumor cells to affect taurine synthesis or modulate sulfur oxidation remains to be determined." (PMID 40842990, 2025). "Additionally, proteins involved in the regulation of the cell cycle (e.g., ATM and STAT3), cell proliferation (e.g., LYN and SRRT), metabolism (e.g., GOT2, PPP1CA, and PYGB), and the regulation of Ca2+ flux (e.g., ANXA6 and CALM1) were also found phosphorylated in the tumor cells." (PMID 40129242, 2025). "Knockdown of GDH, AIAT, or GABAT, but not GOT1, GOT2, or PCb, significantly reduced tumor growth." (PMID 40822358, 2025). "Similarly, in immunodeficient mouse transplantation models, tumor growth did not change after silencing GOT2." (PMID 40247913, 2025). "In PDAC cells, tumor Asp availability was maintained by both de novo synthesis and alternative extracellular sources in the absence of GOT1/GOT2 in vivo." (PMID 39777342, 2024). "While GOT2 is not essential for in vivo proliferation of cancer cells, its interaction with PPARδ constrains the spatial distribution of CD4 + and CD8 + T cells within the tumor microenvironment." (PMID 38459595, 2024). "While the flank tumor milieu in immunocompromised mice is less complex than that of a human PDA tumor, α-smooth muscle actin (αSMA) staining revealed that activated mouse fibroblasts comprised a substantial portion of the microenvironment in tumors regardless of GOT2 status." (PMID 35815941, 2022).
cancer (47 papers, 2006 to 2026). A tumor composed of atypical neoplastic, often pleomorphic cells that invade other tissues. "The GOT1 interactome is enriched with the targets of cancer-associated miRNAs, specifically mir34a - a promising cancer therapeutic, while the GOT2 interactome is enriched with proteins that interact with cancer-associated transcription factors." (PMID 42245720, 2026). "GOT2 encodes a mitochondrial enzyme that maintains aspartate-malate shuttle and redox balance and helps cancer cells to proliferate by raising the intracellular aspartate level." (PMID 36984849, 2023). "According to available RNA-seq data, high expression levels of cCAT-encoding GOT1 and mCAT-encoding GOT2 are detected in several cancer types, including liver, colorectal, prostate, head and neck, cervical, stomach, endometrial carcinomas, and melanoma." (PMID 32882966, 2020). "While the underlying mechanisms of GOT2's dualistic role remain under active investigation, current evidence points to its involvement in the reprogramming of glutamine metabolism, a process that ostensibly supports cancer progression." (PMID 38915066, 2024). "Our findings suggest that perturbations in the levels of GOT1/GOT2 within specific tissues reflect pathophysiological changes beyond tissue damage and have implications for cancer metabolism, immune infiltration, prognosis, and treatment personalization." (PMID 42245720, 2026). "Beyond cancer, GOT2 activity is also critical for cellular differentiation and viability in multiple normal tissues, underscoring its fundamental role in maintaining physiological homeostasis." (PMID 40842990, 2025). "While the role of GOT2 in fatty acid transport is well-established in normal tissues, its biological function in cancer has only recently been uncovered." (PMID 40842990, 2025). "GOT2, a mitochondrial enzyme that has recently garnered considerable interest in cancer metabolism, is a mitochondrial aminotransferase that reversibly catalyzes the conversion of glutamate and oxaloacetate to aspartate and α‐ketoglutarate." (PMID 39350574, 2024). "To better understand the function of GOT2 in cancer cell growth and metabolism, we knocked down its level by RNAi technology." (PMID 37684043, 2023). "According to previous studies, GOT2 promoted the growth and proliferation of malignant tumors mainly through three pathways." (PMID 37693904, 2023). "Based on TCGA data, we conducted the pan-cancer analysis to assess the expression and prognostic significance of GOT2 in various cancers." (PMID 37693904, 2023). "Differential expression analysis showed that GOT2 expression was significantly increased in 22 cancer types, such as ACC, BRCA, and CESC, compared with normal tissues." (PMID 37693904, 2023). "The mechanisms behind GOT2 are still being explored, but it appears it is involved in reprogramming glutamine metabolism in order to promote cancer progression." (PMID 37693904, 2023). "In contrast, GOT2 expression was significantly decreased in 3 cancers, including CHOL, KIRC, and LIHC." (PMID 37693904, 2023). "Survival analyses showed that beyond CM, GOT2 expression also had prognostic significance in other 8 cancer types (all p < 0.05)." (PMID 37693904, 2023). "In cancer studies, miR-520a has been associated with suppression of oncogenic signaling pathways including CDK4, SUV39H1, LIMK1, GOT-2, AKT1/mTOR, and PI3K/AKT31–37." (PMID 35149732, 2022). "We analyzed the pan-cancer correlation between GOT2 expression and Treg cell infiltration in the TCGA database." (PMID 36284275, 2022). "It is probable that cancer cells with high GOT2 expression are addictive in nucleotide synthesis, supporting rapid cell proliferation and thus leading to THF decline." (PMID 30714292, 2019). "A key factor for the S-phase arrest observed in Gln-deprived KRas-driven cancer cells is the production of aspartate in the transamination reaction catalyzed by GOT2." (PMID 26682255, 2015).
cancer (continued). "GOT2 is inhibited by aminooxyacetate (AOA), and importantly, AOA mimics Gln deprivation and causes S-phase arrest in KRas-driven cancer cells and G1 arrest in other cells." (PMID 26682255, 2015). "However, research regarding specific GOT2 inhibitors and their potential therapeutic use in cancers remains very limited." (PMID 40651940, 2025). "There are no reports on the regulatory mechanisms of GOT2 in BCa and the mechanisms governing GOT2 protein stability in human cancers remain largely unknown." (PMID 40651940, 2025). "Therefore, GOT2 not only participates in cancer cell metabolic reprogramming but also plays a pivotal role in shaping an immunosuppressive microenvironment." (PMID 40842990, 2025). "Given the potential roles of taurine and sulfur dioxide in regulating apoptosis, redox balance, and the immune microenvironment, investigating GOT2-mediated sulfur metabolism may offer new insights into cancer metabolic reprogramming." (PMID 40842990, 2025). "Notably, the molecular mechanisms by which cancer cells dynamically allocate aspartate flux between the urea cycle and nucleotide synthesis pathways through GOT2 remain to be systematically elucidated." (PMID 40842990, 2025). "GOT2 is a key component of rewiring of glutamine metabolism in various cancers." (PMID 40651940, 2025). "This multifunctionality positions GOT2 as a potential target for cancer diagnosis and therapy." (PMID 40842990, 2025). "To determine whether GOT2 expression correlates with cancer, we surveyed GOT2 expression in multiple cancer types and adjacent normal tissues through the TIMER database." (PMID 35735610, 2022). "GOT2 expression was lower in cancer stem cells than in HCC cells." (PMID 36284275, 2022). "ScRNA-seq revealed the GOT2 downregulation in cancer stem cells compared with HCC cells." (PMID 36284275, 2022). "We first accessed the pan-cancer expressions of GOT2 in the TCGA database." (PMID 36284275, 2022). "Importantly, through single-cell transcriptomic analysis, we confirmed that GOT2 was down-regulated in cancer stem cells compared with HCC cells." (PMID 36284275, 2022). "Supplementation with the metabolites aspartate and α-ketoglutarate (α-KG) has been shown to rescue cancer cell proliferation by GOT2 inhibition, and another study reported that supplementation with the GOT1 downstream metabolite oxaloacetate could partially rescue viability of GOT1-knockout cells." (PMID 41299514, 2025). "Overall, these results unveiled that ChREBP, by directly regulating GLS1 and GOT2 expression, rerouted Gln metabolism to fuel Asp production and thus support high proliferation rate of HCC cancer cells." (PMID 38424041, 2024). "In cancer cells, conversion of Glut into α-ketoglutarate (α-KG) relies on glutamate dehydrogenase (GLUD1), glutamic-pyruvic transaminase 2 (GPT2) or glutamic-oxaloacetic transaminase 2 (GOT2)." (PMID 38424041, 2024). "However, GOT2 could exhibit a cancer-suppressive profile in some cancers." (PMID 37693904, 2023). "This indicates that the increased conversion of oxaloacetate from L-Asp in cancer occurs mainly in the cytosol and not in the mitochondria, where GOT2 is the only enzyme acting on L-Asp." (PMID 36282866, 2022). "In this study we demonstrate that mitochondrial GOT2 serves to control senescence in PDAC cells through regulation of ROS, suggesting that targeting the unique redox regulatory pathways of PDAC might be an effective strategy to treat these cancers." (PMID 29352139, 2018). "The essentiality of GOT2 in senescence regulation of PDAC, which is dispensable in their normal counterparts, may have profound implications for the development of strategies to treat these refractory cancers." (PMID 29352139, 2018).
infection (12 papers, 2015 to 2025). The state of being infected such as from the introduction of a foreign agent such as serum, vaccine, antigenic substance or organism. "In contrast, GOT2 displayed an inverse trend, with its expression decreasing following infection and subsequently increasing after 12 hpi." (PMID 41171159, 2025). "To elucidate ASFV’s regulatory strategy over GOT1 and GOT2, we mapped the kinetics of their protein expression at various time points post-infection." (PMID 41171159, 2025). "ISKNV mainly promoted the expression of MDH1, GOT1, MDH2 and GOT2 in the early stage of infection and further facilitated energy supply, ultimately promoting the proliferation of ISKNV." (PMID 39459874, 2024). "For further validation, GOT2 was knocked down or overexpressed via lentiviral infection." (PMID 30714292, 2019). "Above results indicated that SCRV infection mainly promoted the expression of GOT1 in the early stage, and promoted the expression of MDH2, GOT2, and ASNS in CPB cells in the late stage." (PMID 37065159, 2023). "Among these genes, glutaminase 1 (GLS1) and glutamate dehydrogenase 1 (GLUD1) enzyme activity and protein expression were elevated, while glutamic oxaloacetic transaminase (GOT1 and GOT2), glutamate pyruvate transaminase 2 (GPT2), and glutamine synthase (GS) were unchanged during PoRVA infection." (PMID 38905309, 2024). "However, neither infection nor Got2 inhibition significantly affected 13C flux into argininosuccinate." (PMID 40880474, 2025). "The lncRNA ACOD1, which is activated by infection with multiple viruses but not by type I IFN stimulation, can bind to and enhance the catalytic activity of the metabolic enzyme glutamic-oxaloacetic transaminase (GOT2), the activity of which is indispensable for viral replication." (PMID 35495674, 2022).
degenerative diseases (2 papers, 2006 to 2017). "Indeed, decreased ATP production has been reported in correlation with decreased GOT2 expression and function in preclinical models of traumatic brain injury and neurodegenerative disease." (PMID 29107957, 2017).
infectious disease (1 paper, 2023). A disorder directly resulting from the presence and activity of a microbial, viral, or parasitic agent in humans. "Got-1, Got-2, and Hpd genes are involved in metabolic changes associated with inflammatory processes and infectious diseases when it is needed to modify protein and amino acid requirements." (PMID 36835523, 2023).
GOT2 also shares sentences with these, for which no sentence is quoted: Obesity (26 papers); Insulin resistance (15); diabetes (11); atherosclerosis (8); myocardial infarction (7); Type 2 Diabetes (7); cardiovascular disease (5); metabolic syndrome (5); Stroke (4); acute myocardial infarction (3); coronary artery disease (3); COVID-19 (3); enterocolitis (3); kidney (3); non-small cell lung carcinoma (3); schistosomiasis (3); Sepsis (3); stable angina (3); acute myeloid leukemia (2); bacteremia (2); colitis (2); Crohn disease (2); dry eye (2); experimental autoimmune encephalomyelitis (2); gastric adenocarcinoma (2); Intellectual disability (2); leukemia (2); melanoma (2); metabolic disease (2); necrotizing enterocolitis (2).
A further 96 diseases each share a sentence with GOT2 in 2 papers or fewer.